WBP4 (WW domain binding protein 4)
Description:
Involved in pre-mRNA splicing as a component of the spliceosome. May play a role in cross-intron bridging of U1 and U2 snRNPs in the mammalian A complex.
Synonyms: FBP21; MGC117310; NEDHFDB
Tractability: Small molecule: a structure with a bound ligand is known. PROTAC: ubiquitination databases record sites on it; its protein half-life has been measured.
Gene: Protein-coding gene on chromosome 13 (41,061,509 to 41,084,006, forward strand). Ensembl gene ENSG00000120688.
Subcellular location: Nucleus; Nucleus speckle
Subcellular location (Human Protein Atlas): Nucleoplasm; Plasma membrane; Vesicles
Pathways (Reactome):
Metabolism of RNA: mRNA Splicing - Major Pathway
Gene Ontology:
Molecular function: proline-rich region binding; protein binding; nucleic acid binding; zinc ion binding
Biological process: mRNA cis splicing, via spliceosome; mRNA splicing, via spliceosome
Cellular component: nuclear speck; nucleoplasm; nucleus; U2-type precatalytic spliceosome; precatalytic spliceosome; spliceosomal complex
Genetic constraint (gnomAD): Loss-of-function variants: 35 observed, 47.79 expected, observed/expected ratio (o/e) 0.73, 90% interval 0.56 to 0.97. The upper end of that interval is the gene's LOEUF score, 0.97, which puts it in group 4 of 6, group 1 being the genes least tolerant of losing a copy. Missense variants: 383 observed, 411.81 expected, observed/expected ratio (o/e) 0.93, 90% interval 0.86 to 1.01. Synonymous variants: 138 observed, 140.52 expected, observed/expected ratio (o/e) 0.98, 90% interval 0.85 to 1.13.
Homologues: Orthologues: chimpanzee WBP4 (99% identical), macaque WBP4 (95% identical), dog WBP4 (86% identical), pig WBP4 (86% identical), rabbit WBP4 (81% identical), guinea pig WBP4 (78% identical), mouse Wbp4 (76% identical), rat Wbp4 (65% identical), tropical clawed frog wbp4 (45% identical), Drosophila melanogaster CG4291 (25% identical).
Diseases named in the same sentence as WBP4 in open-access papers:
WBP4 is named in the same sentence as 1 disease in open-access papers, as found by Europe PMC text mining. Sharing a sentence is not in itself a finding about the gene and the disease. The quoted sentences say what the papers report.
kidney damage (1 paper, 2021). "The other six markers, CDC5L, HNRNPU, NUDT21, PAPOLA, POLR2B, and WBP4, were all negatively correlated with GFR, indicating that these genes may aggravate kidney damage in patients with LN." (PMID 34557492, 2021).